MSMB (microseminoprotein beta)
Synonyms: IGBF; PSP-94; PSP94; PSP57; MSP; MSPB; PN44; PRPS; PSP; HPC13
Tractability: Antibody: UniProt places it where antibodies can reach, with medium confidence; UniProt predicts a signal peptide or a membrane-spanning region; its Gene Ontology location is reachable by antibodies, with medium confidence.
Gene: Protein-coding gene on chromosome 10 (46,033,307 to 46,048,180, reverse strand). Ensembl gene ENSG00000263639.
Subcellular location: Secreted
Gene Ontology:
Molecular function: protein binding
Cellular component: extracellular region; nucleus
Genetic constraint (gnomAD): Loss-of-function variants: 7 observed, 8.03 expected, observed/expected ratio (o/e) 0.87, 90% interval 0.49 to 1.6. That is too few expected variants to judge how well the gene tolerates losing a copy. Missense variants: 121 observed, 138.8 expected, observed/expected ratio (o/e) 0.87, 90% interval 0.75 to 1.01. Synonymous variants: 43 observed, 47.6 expected, observed/expected ratio (o/e) 0.9, 90% interval 0.71 to 1.16.
Homologues: Orthologues: chimpanzee MSMB (98% identical), macaque MSMB (80% identical), pig MSMB (53% identical), rat Msmb (46% identical), mouse Msmb (43% identical), tropical clawed frog msmb.6 (34% identical), zebrafish si:ch73-132k15.2 (24% identical), zebrafish msmbl (23% identical). Paralogues in human: MSMP (19% identical).
Diseases named in the same sentence as MSMB in open-access papers:
MSMB is named in the same sentence as 40 diseases in open-access papers, as found by Europe PMC text mining. Sharing a sentence is not in itself a finding about the gene and the disease. The quoted sentences say what the papers report.
prostate carcinoma (63 papers, 2009 to 2025). A carcinoma that arises from epithelial cells of the prostate gland. "MSMB (microseminoprotein beta) is also a secreted protein that has been extensively analyzed in prostate cancer because of its strong correlation with susceptibility to the disease, changes in expression, and genetic risk." (PMID 41200187, 2025). "NEFH functions as a tumor suppressor, while MSMB encodes a prostate-secreted protein and biomarker for prostate cancer." (PMID 41468516, 2025). "Of these, three protein associations with risk of prostate cancer overall were replicated in men of African ancestry: MSMB [OROverall = 0.85, 95% CI: 0.80–0.91], MMP7 [OROverall = 0.83, 95% CI: 0.73–0.95], and ISLR2 [OROverall = 0.85, 95% CI: 0.73–0.99]." (PMID 38878676, 2024). "For example, a risk allele of the MSMB gene has been reported to be associated with prostate cancer compared to controls, but its association was stronger for non-fatal prostate cancer." (PMID 30337939, 2018). "High expression of the EZH2 gene is also associated with low MSMB levels in metastasizing prostate cancer." (PMID 28410242, 2017). "The minor allele of rs10993994 in the promoter of the MSMB gene has been associated with prostate cancer and it creates a cognate site that is bound by CREB1." (PMID 28186491, 2017). "Genome-wide association studies (GWASs) identified microseminoprotein-β (MSMB) gene rs10993994 polymorphism was significantly associated with prostate cancer (PC) risk." (PMID 28212531, 2017). "Microseminoprotein-beta (MSMB, MSMB) is an abundant secretory protein contributed by the prostate, and is implicated as a prostate cancer (PC) biomarker based on observations of its lower expression in cancerous cells compared with benign prostate epithelium." (PMID 26939004, 2016). "The remaining two variants included one upstream variant at the MSMB locus that was annotated as pathogenic for hereditary prostate cancer, as well as one stop-gain variant within DUOXA2 that was annotated as pathogenic for thyroid dyshormonogenesis." (PMID 27356984, 2016). "For example MSMB which encodes beta-microseminoprotein, a primary constituent of semen and a potential prostate cancer biomarker, and CTBP2, a gene with antiapoptotic activity are located on chromosome 10." (PMID 27609145, 2016). "Loss of MSMB expression shows the same pattern – markedly reduced in all but good outcome iCluster2 – consistent with its reported role in prostate cancer." (PMID 26501111, 2015). "Genome-wide association studies have implicated a handful full of single nucleotide polymorphisms with predisposition to prostate cancer development, specifically in the MSMB gene, which codes for β-microseminoprotein." (PMID 22641253, 2012). "This protein has previously been reported as an early serum biomarker for prostate cancer, but recent refinement has demonstrated that SNPs in the MSMB gene represents a predisposition factor for metastatic prostate cancer." (PMID 22641253, 2012). "The upstream partner, microseminoprotein beta, codes for a constituent of semen and has been shown in two genome-wide association studies to be linked to prostate cancer risk." (PMID 21261984, 2011). "MSMB has been characterized as a tumor suppressor, and lower levels of its product, PSP94, are associated with more aggressive forms of prostate cancer." (PMID 21085629, 2010). "The almost complete loss of MSMB in PIN suggests that reduced MSMB is an early event in tumourigenesis consistent with an association between prostate cancer risk and the rs10993994 genotype." (PMID 20967219, 2010). "Genetic data presented here demonstrate that the chromosome 10q11 prostate cancer risk locus is associated with decreased levels of MSMB and increased levels of NCOA4 RNA expression." (PMID 21085629, 2010).
prostate carcinoma (continued). "This is the first study to describe the relationship between the risk allele of the tag SNP rs10993994 and MSMB levels in benign and tumour prostate tissue and to correlate the protein level with genotype and aggressiveness of prostate cancer." (PMID 20967219, 2010). "Microseminoprotein-beta (MSMB) regulates apoptosis and using genome-wide association studies the rs10993994 single nucleotide polymorphism in the MSMB promoter has been linked to an increased risk of developing prostate cancer." (PMID 20967219, 2010). "MSMB, a gene coding for β-microseminoprotein, has been identified as a candidate susceptibility gene for prostate cancer (PrCa) in two genome-wide association studies (GWAS)." (PMID 19997100, 2010). "This is mostly in agreement with our findings, which suggest a major shift in MSMB expression in association with prostate cancer." (PMID 20569440, 2010). "There is strong evidence linking the rs10993994 SNP in the MSMB promoter region to an increased risk of developing prostate cancer." (PMID 20967219, 2010). "The demonstration of a similar association with urinary MSMB and MSMB staining in benign prostate tissue reinforces the causal association between MSMB expression and prostate cancer." (PMID 20967219, 2010). "Our study reveals that SLC14A1, ARHGEF38, NEFH, MSMB, KRT23, and KRT15 are potential diagnostic biomarkers for prostate cancer, among which MSMB may play a protective role in prostate cancer." (PMID 40260298, 2025). "MSMB is a secretory protein and member of the human immunoglobulin family that is released largely by luminal epithelial cells in the prostate epithelium and has a documented role in overall prostate cancer risk for both observational and genetic epidemiology." (PMID 38878676, 2024). "Finally, using spatial transcriptomics data, we demonstrated a central role for the gene of our most robustly associated prostate cancer protein, MSMB, in distinguishing benign from undifferentiated, high-grade prostate cancer cells." (PMID 38878676, 2024). "Results showed coffee consumption (OR=0.91, 95%CI: 0.83-0.99), microseminoprotein-beta (OR=0.96, 95%CI: 0.95-0.98), and pubertal development (OR=0.97, 95%CI: 0.94-1.00) may be causal protective factors of prostate cancer." (PMID 35237523, 2022). "MSMB encodesβ-microsemino protein, which is a proposed biomarker for prostate cancer." (PMID 22496748, 2012). "The promoter location of the risk allele, and its ability to reduce promoter activity, suggested that the rs10993994 risk allele could result in lowered MSMB in benign tissue leading to increased prostate cancer risk." (PMID 20967219, 2010). "Our findings raise the possibility that urinary MSMB related to genotype may be a useful biomarker for screening for prostate cancer risk and development." (PMID 20967219, 2010). "Human beta-microseminoprotein (MSMB) is synthesized from a gene located on chromosome 10, which has recently attracted much attention since genome wide association studies identified it to be connected with prostate cancer susceptibility." (PMID 19737427, 2009). "The consistent downregulation of MSMB, a known tumor suppressor in prostate cancer, further supports its role in inhibiting tumor progression." (PMID 40260298, 2025). "This study presents an integrative strategy combining bioinformatics, transcriptomics, and experimental validation to identify SPON2 and MSMB as promising secretory biomarkers for prostate cancer." (PMID 41200187, 2025). "Despite the promising identification of SPON2 and MSMB as secreted, tumor-enriched biomarkers for prostate cancer, several limitations warrant consideration." (PMID 41200187, 2025). "Previous studies have indicated notable clinical relevance associated with microseminoprotein-beta (MSMB) and epithelial cell adhesion molecule (EPCAM) for prostate cancer." (PMID 39443867, 2024).
prostate carcinoma (continued). "In this study, MSMB was one of only two proteins (including TPM3) to significantly associate and colocalise with all three prostate cancer outcomes." (PMID 38878676, 2024). "MT1G, MSMB, SLC22A3, COMP and KRT15 have also been associated with aggressive and/or poor clinical outcome in prostate cancer." (PMID 36661662, 2022). "Microseminoprotein beta (MSMB) has been reported to be downregulated in prostate cancer tissues and in patient serum." (PMID 33564686, 2021). "Several researches have shown the lower expression of MSMB protein in prostate cancer tissue and the cancer suppressive role in prostate cancer." (PMID 34054930, 2021). "MSMB has inhibin-like activity, inhibits growth of cancer cell lines, and was often found reduced or even lost in prostate cancer tissue." (PMID 33114768, 2020). "A read-through fusion transcript of NCOA4 and MSMB has recently been demonstrated in some prostate cancers." (PMID 26939004, 2016). "This SNP was subsequently associated with PSA levels in unaffected men, as were other prostate-cancer related SNPs in the hepatocyte nucleartor-1 β (HNF1B) and β-microseminoprotein (MSMB) genes." (PMID 26431041, 2015). "Very little is known of MSMP, which is similar to MSMB but more highly conserved among species, apart from its expression in a prostate cancer cell line." (PMID 22208949, 2011). "In particular, a small peptide derived from the MSMB protein has been shown to exhibit anti-tumor properties and has been suggested as a potential therapeutic agent in prostate cancer." (PMID 22141344, 2011). "Several groups have studied MSMB expression in prostate cancer and all have found higher levels of MSMB in benign and normal tissue or serum when compared with material from tumours." (PMID 20967219, 2010). "Our results indicate that the amount or nature of mRNA transcripts expressed from the LMTK2, HNF1B and MSMB candidate genes is altered in prostate cancer, and provides further evidence for a role for these genes in this disorder." (PMID 20569440, 2010). "MSMB has been studied by a large number of groups as a putative prostate cancer biomarker because levels in tissue and serum is reduced or lost with cancer development." (PMID 20967219, 2010). "We found highly significant disturbances to the profile of isoforms expressed in prostate cancer in the case of the MSMB and HNF1B genes." (PMID 20569440, 2010). "We also report a potential role for alternative mRNA processing of the HNF1B and MSMB genes in the aetiology of prostate cancer." (PMID 20569440, 2010). "Among secretory proteins implicated in prostate cancer are SPON2, MSMB and AGR2." (PMID 41200187, 2025). "SPON2 and MSMB are secretory, immunogenic biomarkers overexpressed in prostate cancer." (PMID 41200187, 2025). "Previous studies have demonstrated that MSMB plays a tumor suppressor role in prostate tissue, and its over-expression can inhibit growth, invasion, and metastasis as well as promote apoptosis in prostate cancer (PCa) cells." (PMID 39205920, 2024). "Over expression of MSMB could induce PC cell apoptosis and suppress prostate cancer growth, invasion and metastasis." (PMID 28212531, 2017). "The MSMB levels are low in prostate cancer, as compared to the benign prostate disease." (PMID 27351008, 2014). "MSMB shows high expression in normal stomach and lung cancer samples, in addition to prostate samples, and appears to show higher expression in prostate normal samples than in prostate cancer samples." (PMID 21261984, 2011). "Interestingly, MSMB has been found decreased in prostate cancer and has been suggested to function through its ability to regulate apoptosis." (PMID 22141344, 2011). "We discuss how, as a component of the marsupial postovulatory coats, USM could provide important clues for elucidating the roles of MSMB and other related proteins, with possible applications in prostate cancer, immunity and fertility control." (PMID 22208949, 2011).
prostate carcinoma (continued). "Consistent with the loss of MSMB in tumourigenic glands we have demonstrated a highly significant loss of MSMB in urine from patients with both low and high Gleason grade prostate cancer was compared to those with no known prostate disease." (PMID 20967219, 2010). "However, in cancer tissues, there is a near complete switch to isoform MSMB1, which is present at 96% total MSMB expression in prostate cancer." (PMID 20569440, 2010). "If an association between genotype and expression of MSMB or NCOA4 were observed in tissue other than prostate, then that gene may be less likely to be involved in prostate cancer risk." (PMID 21085629, 2010). "Because regulatory elements can interact with many genes, and since both MSMB and NCOA4 are strong candidates for prostate cancer risk, we evaluated the relationship between risk allele status and transcript abundance of these genes across both normal and tumor prostate tissues." (PMID 21085629, 2010). "We found that the genes SLC14A1, MSMB, KRT23, and KRT15 are primarily enriched in “prostate cancer” signaling pathway." (PMID 40260298, 2025). "Factor 10 displays the highest signal in normal glands, with high expression of MSMB and AZGP1, which are reported to be significantly downregulated in prostate cancer." (PMID 40167331, 2025). "As expected, KLK3 Ct values strongly correlated with Ct values of other genes which have been reported to play a role in prostate cancer (i.e., PCA3, AMACR, TRPM8, MSMB and PSGR)." (PMID 32630458, 2020). "A few, mostly nested case–control studies have reported lower ENL concentrations in prostate cancer cases than in controls, with one study also reporting an interaction between an ENL and an SNP in the MSMB gene." (PMID 28884432, 2018). "Rs10993994 on 10q11 is proximal to the promoter region of MSMB, a urinary biomarker that outperforms urinary PSA at differentiating men with prostate cancer at all Gleason grades." (PMID 29560112, 2018). "Concordance was now observed only for three phenotypes (inflammatory bowel disease, prostate cancer, obesity-related phenotypes) and a total of 3 genes (MST1, MSMB and SH2B1, respectively)." (PMID 21072174, 2010). "MSMB and EPCAM could be prostate cancer-relevant indicators or contributors in various medical and pathological conditions, underscoring the importance of further exploration and validation." (PMID 39443867, 2024). "Moreover, in prostate cancer, EZH2 can repress the expression of tumor suppressors such as DAB2IP, p16 (CDKN2A), CDK4, E-cadherin (CDH1), MSMB, Ras (KRAS), NF-κB (NFKB1), EMT regulator." (PMID 27835578, 2016). "Genes typically associated with prostate cancer are evident: PCA3 and GDF15 levels are elevated, and TP63 and MSMB levels are reduced across all tumour subgroups, and are not subtype-specific." (PMID 26501111, 2015). "We determined urinary levels of MSMB in 215 normal/benign men with no history of prostate disease and 89 men with prostate cancer." (PMID 20967219, 2010). "Urine is a highly acceptable biological measure for patients and our findings indicate that MSMB is a potential target for further investigation as a urinary biomarker for prostate cancer screening and diagnosis, without the need for a digital rectal exam." (PMID 20967219, 2010). "Accordingly, MSMB expression has previously been reported to be a positive prognostic indicator in prostate cancer, although both these studies measured total, not isoform-specific expression levels." (PMID 20569440, 2010). "We report here that disruption of the amount or nature of transcripts expressed from the LMTK2, MSMB and HNF1B genes, identified in the genome wide scans for prostate cancer, may be important in the aetiology of this disorder." (PMID 20569440, 2010). "This window lies not in MSMB but in a neighboring gene, NCOA4, also a candidate gene for prostate cancer risk." (PMID 20976246, 2010).
prostate carcinoma (continued). "Although the mechanism of action for MSMB in prostate cancer is not clear, MSMB has been shown to have a regulatory effect on cell growth, which may be lost during tumourigenesis while a MSMB-derived polypeptide was shown to induce prostate cell death." (PMID 38878676, 2024). "The SNPs identified are mainly in regions that had not previously been known to be associated with prostate cancer risk that might be clinically relevant, such as MYC, MSMB, KLK2 and KLK3 genes." (PMID 27819754, 2017). "Unlike PSA, previous reports have suggested that MSMB levels are unaffected by hormone ablation therapy frequently used in prostate cancer treatment and we need to determine if MSMB might be useful in monitoring disease burden in patients undergoing various forms of treatment." (PMID 20967219, 2010).
prostate tumors (6 papers, 2010 to 2025). "qRT-PCR validation in clinical samples confirmed significant overexpression of SPON2 (~18-fold) and MSMB (~2.6-fold) in prostate tumor tissues compared to matched normal tissues." (PMID 41200187, 2025). "The differential expression observed in the microarray analysis was further validated by qRT-PCR for two candidate secreted biomarkers, SPON2 and MSMB, using RNA extracted from prostate tumor tissues (n = 5) and their matched adjacent normal tissues (n = 5)." (PMID 41200187, 2025). "Moreover, it has been shown by other authors that prostate tumors could interact with the surrounding benign prostate epithelium, by downregulating some biomarkers (i.e., microseminoprotein-beta, MSMB), and that this response could be associated with tumor aggressiveness." (PMID 35406395, 2022). "MSMB codes for a secreted seminoprotein, which has tumour suppressor properties and is thought to be silenced in prostate tumour tissues by the enhancer of zeste homolog 2 (EZH2) protein." (PMID 20569440, 2010). "Additionally, in a rodent model and in vitro, higher MSMB activity was found to suppress prostate tumour growth while a knockout of MSMB promoter/enhancer regions was characterized by tumour progression and metastases." (PMID 38878676, 2024).
benign prostatic hyperplasia (5 papers, 2010 to 2021). A non-cancerous nodular enlargement of the prostate gland. "MSMB protein expression is higher in healthy prostate tissue or benign prostatic hyperplasia (BPH) compared to PC." (PMID 33488712, 2021). "The transcript levels of MSMB, nuclear receptor co-activator 4 (NCOA4) and MSMB-NCOA4 fusion were examined by qRT-PCR in prostatectomy samples and by RNA-sequencing in benign prostatic hyperplasia, PC, and CRPC samples." (PMID 26939004, 2016).